EYA1 (EYA transcriptional coactivator and phosphatase 1)
Diseases named in the same sentence as EYA1 in open-access papers (continued):
Sharing a sentence is not in itself a finding about the gene and the disease.
tumor (21 papers, 2008 to 2025). "In addition, we found that high expression of EYA1 in ccRCC patients was significantly associated with clinicopathological parameters, including pathological stage, tumor grade, shorter OS, and PFI (progress free interval)." (PMID 37156847, 2023). "In the nude mouse model, Eya1 suppression significantly reduced tumor volume and weight compared to the control groups." (PMID 39897043, 2025). "To analyze EYA1 expression pattern across various tumors, we first employed Tumor Immune Single Cell Hub (TISCH), a database collecting 2,045,746 cells from 28 types of human cancers." (PMID 39897043, 2025). "To examine the role of BCL2L12 in EYA1's tumor-promoting effects, we overexpressed BCL2L12 in EYA1-knockdown cells." (PMID 39897043, 2025). "In the intracranial tumor transplantation mouse model, tumor formation was also inhibited by suppressing Eya1." (PMID 39897043, 2025). "Both TIMP2 and EYA1 proteins have been identified as tumour promoters in various cancers inducing cell migration and tumour metastasis." (PMID 36397137, 2022). "Both EYA1 and PRKRA are involved in cell proliferation and migration and implicated in tumour suppression and angiogenesis." (PMID 34034517, 2021). "Intriguingly, we observed that EYA1 overexpression dramatically facilitated tumour growth, but OTUB1 downregulation significantly suppressed this trend." (PMID 34773364, 2021). "The in vitro and in vivo experiments found that EYA1-expressing tumor cells promoted HUVEC migration and tube formation by regulating VEGF-A, but the expression of VEGF-A was inhibited when eliminating EYA1." (PMID 32456711, 2020). "To identify the expression pattern of SIX1 and EYA1 in human thyroid tissue as well as tumor, we performed IHC analysis by using two tissue microarrays (TH8010 and TH802a)." (PMID 31921695, 2019). "Increased EYA1 protein expression is highly correlated with increased mitotic rate and tumor thickness." (PMID 29285235, 2017). "Marker genes differentially expressed in the blastemal tumours relative to triphasic tumours included CM (EYA1, HOXA10, NR2F2) and PA (WT1) genes." (PMID 29040332, 2017). "Tumor clusters c5-c8 expressed higher levels of blastemal markers, such as EYA1 and PAX2." (PMID 40098972, 2025). "Notably, the lowest mRNA expression of EYA1/2 was observed in tumor grade 2, whereas the lowest mRNA expression of EYA3/4 was found in grade 4." (PMID 37156847, 2023). "EYA1-4 proteins can influence tumour progression through several mechanisms." (PMID 34021172, 2021). "At the molecular level, ATXN8OS sponged a tumor-suppressive miR-424-5p, thereby activating key oncogenes such as EYA1, DACH1, and CHRM3, which could be suppressed by Rg3 treatment." (PMID 33477683, 2021). "Our study also showed that EYA1 is responsible for SIX1-induced STAT3 signaling activation, indicating disruption of EYA1 function may suppress the SIX1-mediate tumor growth in PTC." (PMID 31921695, 2019). "However, our previous study also indicated that transactivation of cyclin D1 through the tyrosine-phosphatase activity of EYA1 is required for tumor growth and cellular proliferation." (PMID 27203207, 2016). "We found that the levels of SIX1 and EYA1 expression were significantly associated with age, lymph node metastasis (two sample missed this information, tissue ID: Etg030430 and Etg030007) and clinical stage, but not tumor size." (PMID 31921695, 2019). "Among the remaining hub genes, the eya-1 mammalian orthologs promote development of tissues and organs whereas the sma-4 ortholog SMAD4/DCP4 acts as a tumor suppressor." (PMID 18752680, 2008). "The Eyes Absent proteins (EYA1-4) are a biochemically unique group of tyrosine phosphatases known to be tumour-promoting across a range of cancer types." (PMID 38360978, 2024).
tumor (continued). "The Eyes Absent Family (EYA1-4) is a unique group of dual-function proteins with oncogenic roles in a variety of tumour types, where they promote cancer cell phenotypes such as proliferation, survival, and migration." (PMID 38360978, 2024). "Finally, we show that EYA-mediated dephosphorylation of PLK1 supports PLK1 function during mitotic progression, while treatment with an EYA phosphatase inhibitor potently elicits cell death in tumour cells expressing EYA4 and/or EYA1." (PMID 38360978, 2024). "The research above indicated that the role of EYA1/4 in ccRCC might be the same as the role of EYA1/4 in HCC, which served as a potential oncogene and a tumor suppressor, respectively." (PMID 37156847, 2023). "The results showed that overexpression of EYA1 could contribute to ccRCC development, while low expression of EYA3/4 might have a tumor-suppressive effect." (PMID 37156847, 2023). "The increased expression of EYA1 might play an important role in ccRCC oncogenesis, and the decreased expression of EYA3/4 could function as a tumor suppressor, suggesting EYA1/3/4 might serve as valuable prognostic markers and potential new therapeutic targets for ccRCC." (PMID 37156847, 2023).
cancer (14 papers, 2007 to 2025). A tumor composed of atypical neoplastic, often pleomorphic cells that invade other tissues. "In comparison with normal tissue, high expressions of SIX1 and EYA1 were associated with a malignant tumor." (PMID 31921695, 2019). "Each gene in this network (gcn-1, abcf-3, sptf-3, pig-1, egl-1, ceh-34 and eya-1) has a human counterpart, some of which are implicated in human diseases, including developmental disorders and cancer." (PMID 25101958, 2014). "Intriguingly, SIX1 was tightly linked to EYA1 in malignant tumor." (PMID 31921695, 2019). "Additionally, aberrant activity of human homologs of EYA (EYA1–4) have been linked to oncogenesis in a variety of cancers." (PMID 28713571, 2016). "While future work is needed to reveal how Eya1’s activities are related to tissue and cell type as well as genetic context, our findings provide insight into the underlying molecular mechanisms by which increased Eya1 activity leads to various types of cancer and their metastasis." (PMID 36130284, 2022). "Aberrant expression of EYA1 was found in multiple cancers, and it showed that EYA1 plays an oncogenic role in regulating progression of cancer." (PMID 34773364, 2021). "EYA1 was reported to regulate VEGF-A during angiogenesis through HIF-1α signaling pathway in a cancer model, which is consistent with our findings in the PA animal model." (PMID 32456711, 2020). "EYA1 exists in both the nucleus and cytoplasm and it has been recently shown that the role of aberrant EYA1 activity in cancer is likely to be related to its nuclear functions." (PMID 28713571, 2016). "These nuclear activities of EYA1 may mediate cancer cell proliferation, metastasis and chemoresistance." (PMID 28713571, 2016). "EYA1 has shown ambiguous expression profiles across a number of known cancers." (PMID 26370624, 2015). "In the absence of NK1R, the matrix Nkx2-5_02 had a predominant participation driving 8 transcripts, which includes those involved in cancer (EYA1, Trail, HSF1, and ELK-1), smooth-to-skeletal muscle trans-differentiation, and Z01, a tight-junction protein, expression." (PMID 17519035, 2007). "However, a significant increase in SIX1 and EYA1 was detected in malignant tumor, including FTC (p = 0.011, p = 0.038; respectively), MTC (p = 0.006, p = 0.043; respectively), PTC (p < 0.001, p < 0.001; respectively) and ATC samples (p = 0.002, p < 0.001; respectively)." (PMID 31921695, 2019). "Further, benzarone caused a dose-dependent elevation in cleaved PARP, indicative of cell death, and phosphorylation of H3 on S10, indicative of mitotic arrest, in cancer cell lines with high expression levels of EYA4 (HeLa), EYA1 (SKNAS), or both (SKNFI)." (PMID 38360978, 2024). "To begin, we explored the dysregulated transcriptional levels of the EYAs (EYA1, EYA2, EYA3, EYA4) family in 34 types of human common cancer." (PMID 37156847, 2023). "However, current studies on the synergistic effects of EYA1, SIX1, and DACH1 in promoting angiogenesis predominantly focus on cancer-related aspects, leaving the role of these genes in normal tissue differentiation incompletely understood." (PMID 41329538, 2025). "EYA1 which was a classifier protein for separating healthy controls with subjects in Grade II and Grade IV belongs to eyes absent (EYA) family of evolutionarily conserved proteins and is known to have putative role in innate immunity, DNA damage repair, angiogenesis and cancer metastasis, etc." (PMID 26370624, 2015).
kidney disease (5 papers, 2019 to 2025). "In an Australian study, 18 of 178 children with CAKUT were shown to have CNVs in genes known to be associated with kidney disease including EYA1." (PMID 39945861, 2025). "In fact, pathogenic variants in various genes responsible for inherited kidney diseases (patients with NPHS1, EYA1, LAMB2, and CLCN5 gene mutations) were detected by NGS in our study." (PMID 31364286, 2019).
infection (2 papers, 2021 to 2022). The state of being infected such as from the introduction of a foreign agent such as serum, vaccine, antigenic substance or organism. "The specific expression levels of Pax2, Pax8, Eya1, Six1, and Dlx5 in cells from the J1-6d infection scheme were significantly lower than those in the cells infected with NC-shRNA, as shown by semi-quantitative RT-PCR (p < 0.01)." (PMID 34940631, 2021).
benign tumor (1 paper, 2019). "In comparison with normal tissue, SIX1 and EYA1 kept low expression in benign tumor and no statistic difference was found for either SIX1 or EYA1 between groups." (PMID 31921695, 2019).
genetic disorders (1 paper, 2009). "Several of these, including KAL1, DFNB59 and EYA1 are associated with human genetic disorders that lead to sensory defects." (PMID 19636377, 2009).
myopathy (1 paper, 2025). A disease of the muscle in which the muscle fibers do not function properly. "Collectively, our findings uncover a novel role for the Six1/Eya1 axis in modulating muscle remodeling and fibrosis in TED and provide a foundation for the development of targeted therapies for TED-associated myopathy." (PMID 41227354, 2025). "In our study, we investigated whether Six1 and Eya1, key regulators of myogenesis, modulate the progression of fibroblasts to the myofibroblast phenotype, a critical factor in TED myopathy." (PMID 41227354, 2025).
EYA1 also shares sentences with these, for which no sentence is quoted: Hearing impairment (4 papers); renal coloboma syndrome (3); diabetes (2); kidney failure (2); otofaciocervical syndrome (2); Waardenburg syndrome (2); 3MC syndrome (1); amyotrophic lateral sclerosis (1); Anterior polar cataract (1); cleft lip (1); conductive hearing loss (1); cryptorchidism (1); DiGeorge syndrome (1); dilated cardiomyopathy (1); duodenal ulceration (1); Epstein syndromes (1); focal glomerulosclerosis (1); ganglioneuroma (1); gastric cancer (1); Hypermetropia (1); hyperuricemia (1); kidney tumors (1); lung carcinoma (1); lung fibrosis (1); malignant peripheral nerve sheath tumor (1); melanocytic neoplasms of the (1); mesomelia-synostoses syndrome (1); metastatic melanoma (1); Micropenis (1); microtia (1).
A further 21 diseases each share a sentence with EYA1 in 1 paper.